RB1 (RB transcriptional corepressor 1)
Diseases named in the same sentence as RB1 in open-access papers (continued):
Sharing a sentence is not in itself a finding about the gene and the disease.
small cell lung carcinoma (continued). "We then compared these changes to molecular events in RB1−/− Retinoblastoma tumors and Small Cell Lung Cancer (SCLC) to understand how alterations within model pRB-depleted RPE1 cells compared to primary patient samples." (PMID 34404904, 2021). "Here, the authors study the disease using multi-omics technology and find frequent RB1 disruptions and similarities to small cell lung cancer, opening potential therapeutic avenues." (PMID 34145257, 2021). "In small cell lung cancer (SCLC), Aurora B is required for the survival of RB1-deficient cancer cells." (PMID 33542222, 2021). "Frequent overexpression of the miR-17~92 cluster in small cell lung cancer is a fine-tuner to reduce excessive ROS-induced DNA damage in RB1-inactivated small cell lung cancer cells." (PMID 31816897, 2019). "Small cell lung cancer is a highly aggressive disease that exhibits rapid growth and genetic instability including inactivated tumor suppressor retinoblastoma 1 (RB1) and amplified MYC proto-oncogene (MYC)." (PMID 31816897, 2019). "E2F, another cell cycle regulator, positively controls EZH2 transcription through its direct binding on EZH2 promoter upon Rb/RB1 phosphorylation in bladder and small cell lung cancer." (PMID 29556394, 2018). "In small cell lung cancer (SCLC), for example, the prevalence of RB1 loss is more than 90%, while RB1 function in cervical cancer is suppressed by directly associating with HPV-E7 oncoprotein at a frequency of at least 90%." (PMID 21447152, 2011). "The increased expression of p18 in proliferative MM cells is reminiscent of the increased expression of p16INK4a in small cell lung cancer tumors that have inactivated the RB-1 gene." (PMID 17049078, 2006). "Prior and our data support that deregulation of the Rb1-p16 pathway, as confirmed by immunohistochemistry and next-generation sequencing, plays a critical role in the histogenesis of colorectal NECs, as it does in small-cell lung cancer." (PMID 33737597, 2021).
small cell lung carcinoma (continued). "The RB1 gene is inactivated in most cases of specific cancer types such as retinoblastoma, small cell lung cancer (SCLC) and osteosarcoma, whereas alterations of its family members p107 and/or p130 is still a matter of debate, being rarely mutated in human tumors." (PMID 27966456, 2017). "Recent work has suggested that Notch signaling may be important in mouse models of small-cell lung cancer, one of the most common types of RB1 mutant cancers." (PMID 27401552, 2016). "Small cell lung cancer (SCLC) and small cell esophageal cancer (SCEC) have elevated SOX2 and low RB1 and the two genes reduce inhibition of proliferation." (PMID 36835562, 2023). "The retinoblastoma protein 1 (RB1) expression is absent in over 95% of small cell lung cancers (SCLCs) but only 50% of big cell neuroendocrine tumors." (PMID 39310409, 2024).
small cell lung carcinoma (continued). "We found that uterine cervical and small cell lung cancers were predicted to be RB-negative at high prevalence, while most uterine endometrial and stomach cancers were predicted to be RB1-positive by the CCND1/CDKN2A assay." (PMID 21447152, 2011). "Thus Rbl1 and Rbl2 have tumor suppressor activity in the context of small cell lung cancer, but it is only revealed in the absence of RB1." (PMID 35368709, 2022). "Lastly, a CCND1/CDKN2A assay with clinical samples showed that uterine cervical and small cell lung cancers known to have a high prevalence of RB1-decifiency were predicted to be 100% RB1-negative, while uterine endometrial or gastric cancers were predicted to be 5-22% negative." (PMID 21447152, 2011).
cervical carcinoma (120 papers, 1997 to 2026). A carcinoma arising from either the exocervical squamous epithelium or the endocervical glandular epithelium. "More recently, cervical cancer with Rb1 mutation is reported to be more sensitive to cisplatin through PI3K/AKT pathway." (PMID 33664766, 2021). "Loss of RB1 function, which is a well known phenomenon in cervical cancer leads to expression of Cyclin D1, over-expression/amplification of CDK4, and/or loss of the CDKN1B, CDKN2A and CDKN2B." (PMID 26701206, 2016). "In cervical cancer, the TCGA’s 2017 integrated genomic characterization study reported LOF mutations in RB1 (13q)-sensitize tumors to cisplatin through altered PI3K/AKT signaling." (PMID 40565600, 2025). "Although we did not detect any RB1 mutations in our HPVU cervical tumor specimens, both HPVU cervical cancer cell lines C33A and HT3 were found to harbor RB1 mutations according to the COSMIC cell lines database." (PMID 34572780, 2021). "Rb-1 was detected as the driver mutation in this subgroup, suggesting that HPV integration unregulated lots of genes via methylation, especially the driver gene Rb-1, abrogated cell cycle arrest, and stimulated proliferation in cervical cancer." (PMID 33664766, 2021). "This is evidenced in cervical cancer, where the presence of the human papilloma virus E7 protein inactivates RB1 and allows ELF1 to switch from a repressor of proliferation to an activator of proliferation." (PMID 30603056, 2018). "It is important to note that the methylated status of RB1 was considered to be associated with HPV infection (p = 0.042), revealing an important role for HPV in cervical cancer epigenetics." (PMID 26032781, 2015). "In conclusion, our results showed that the methylation status of both genes increased with disease progression, revealing a significant correlation between RB1 methylation and cervical cancer." (PMID 26032781, 2015). "In cervical cancers infected with HPV, the function of RB1 is lost due to association with the E7 oncoprotein." (PMID 21447152, 2011). "To further investigate a possible pRB-mediated E7 stabilization in cervical-cancer-derived cell lines, we generated stable cell lines of SiHa, CaSki, HeLa, and C-4 I expressing control shRNAs or shRNAs targeting pRB (RB1) by lentiviral transduction and puromycin selection." (PMID 40130877, 2025). "In cervical cancer, retinoblastoma (RB1) is a tumor suppressor protein regulated by PTEN." (PMID 36232606, 2022). "Surprisingly, there are other tumor types where there is essentially no selection for deletion of RB1 for example in kidney cancers or cervical cancer, even though there is substantial single copy loss." (PMID 32242058, 2020). "Interestingly, the reduced expression occurs even in tumors where RB1 activity is compromised via other mechanisms (e.g., cervical cancer)." (PMID 32242058, 2020).
cervical carcinoma (continued). "A caveat of our present study was that we were unable to assess palbociclib sensitivity using HPVU cervical cancer cell lines due to the C33A and HT3 cell lines harboring RB1 mutations, and palbocilib sensitivity has been previously reported to be dependent on intact RB1 signaling." (PMID 34572780, 2021). "Additionally, RB1 mutations have not been identified as frequently mutated in cervix cancer cohorts from other independent studies." (PMID 34572780, 2021). "Herein, we investigated the regulation of Eag1 by RB1 in HeLa cervical cancer cells because these cells are HPV-positive, express both Eag1 channels and RB1, and are very suitable for transfection." (PMID 31973216, 2020). "RB1 activity has been much investigated in HPV-positive SCCHN and cervical cancer, but less so in HPV-negative disease." (PMID 26265441, 2015). "Cervical cancer and SCLC, which are known to be the tumor types with a higher frequency of dysfunctional RB1, showed lower CCND1/CDKN2A ratios compared with endometrial and gastric cancers." (PMID 21447152, 2011). "The methylation status of both genes increased with disease progression, showing the lowest frequencies in the control (6.7% for RB1 and 13.3% for CDH1) and LSIL samples (5.8% for RB1 and 11.8% for CDH1) and the highest in cervical cancer samples (50.0% for RB1 and 33.3% for CDH1)." (PMID 26032781, 2015).
glioma (116 papers, 1994 to 2025). A benign or malignant brain and spinal cord tumor that arises from glial cells (astrocytes, oligodendrocytes, ependymal cells). "Among high-grade gliomas with intense and diffuse p16 expression, all except one showed a loss of Rb1 expression." (PMID 36900302, 2023). "For instance, TILs are enriched in NF1 and RB1 mutated gliomas but depleted in EGFR-amplified and PTEN-deleted gliomas." (PMID 35203421, 2022). "It has also been reported in previous study that down-regulation of RB1 gene in glioma was associated with increased cell proliferation and decrease survival in more than one-third of patients." (PMID 32373934, 2020). "The top three genes found in the Glioma signaling network, CCND1, CDKN2A, and RB1, are frequently overexpressed, mutated, and/or deleted in glioma]." (PMID 29912931, 2018). "Loss of RB1 or other components of the RB1 pathway has been associated with decreased survival of patients with high-grade gliomas." (PMID 20520772, 2010). "Interestingly, the type of mutations in RB1 was different in glioma patients and neurodegenerative patients." (PMID 38637503, 2024). "The loss of Rb1 expression, present in all our cases except one, is probably linked to Rb1 deletion, which has already been described in this high-grade subtype and is related to poor prognosis in some glioma subtypes." (PMID 36900302, 2023). "In grade 4 gliomas, the incidence of its mutation can be found in up to 70% of cases, and its absence leads to the activation of the gliomagenesis process by activating the Rb1 pathway." (PMID 36136867, 2022). "From the analysis above, we observed that several cell cycle related genes, such as CDKN2A/2B (14% vs. 3%), CDK4 (10% vs. 0) and RB1(10% vs. 0), were dominant in recurrent gliomas as compared to primary gliomas, so we further clustered the mutated genes according to their functional characteristics." (PMID 31690770, 2019). "Genetic studies have shown that the RB1 mutation is more frequent in hemispheric high-grade gliomas than brain stem tumors, which might explain the higher susceptibility to Delta-24-RGD replication and the higher cytotoxic effect observed in the pHGG cells compared with those in the DIPG cells." (PMID 31138805, 2019). "In high-risk gliomas, recurrent CNVs—such as chromosome 7/12 amplifications (EGFR, CDK4/MDM2) and chromosome 1/8/13 deletions (CHD5, DLC1, RB1)—play pivotal roles in promoting proliferation, immune evasion, and DNA repair defects." (PMID 40636690, 2025).